LEP (leptin)
Diseases named in the same sentence as LEP in open-access papers (continued):
Sharing a sentence is not in itself a finding about the gene and the disease.
papillary thyroid cancer (16 papers, 2011 to 2024). "Additionally, leptin serum levels differentiated the follicular variant of papillary thyroid cancer (FVPTC) from the follicular adenomas (FA) (P < 0.001) and from goiters (P < 0.001)." (PMID 25810718, 2015). "In a study on papillary thyroid carcinoma cells, researchers reported that supraphysiological doses of leptin stimulated both proliferation and migration in vitro." (PMID 39201370, 2024). "Lin and co-workers have identified certain genes whose transcription is modulated in papillary thyroid carcinoma cells by leptin." (PMID 32645835, 2020). "An endogenous anti-appetite factor, leptin has also been shown to support the growth of certain tumors, including papillary thyroid carcinoma, that express the leptin receptor." (PMID 32645835, 2020). "In this study, we analyzed the effects of leptin on two human papillary thyroid cancer (PTC) cell lines, focusing on the molecular mechanisms underlying leptin's effects on cell viability and migration." (PMID 30906321, 2019). "In this study, we estimated serum concentrations of leptin, adiponectin, chemerin, interleukin-6 (IL-6), and vitamin D in patients with papillary thyroid cancer (PTC)." (PMID 30627158, 2018). "The effects of OB3 and leptin on the expression of integrin αvβ3 in papillary thyroid cancer cell lines were similar to those observed in anaplastic thyroid cancer cells." (PMID 27050378, 2016). "The present study was designed to investigate the relation between serum levels of leptin and well-differentiated thyroid carcinoma (WDTC) and to evaluate its correlation with patient and tumor characteristics." (PMID 24867470, 2014). "Our data showed that the serum leptin levels of Iranian patients with papillary thyroid carcinoma were significantly higher than those in control group subjects." (PMID 22007338, 2011). "Strongly high leptin level in papillary thyroid cancer patients in comparison with health subject potentially suggests leptin as a peptide marker of papillary thyroid cancer." (PMID 22007338, 2011). "The aim of this study was determining the serum leptin levels in patients with papillary thyroid cancer and its comparison with healthy subjects." (PMID 22007338, 2011). "Importantly, in the combined treatment, Acrp30 and leptin exert antagonizing effects on papillary thyroid cancer cells’ migration and invasion in both BCPAP and K1 cell lines." (PMID 33587254, 2021). "Thyroid hormone may increase adipocyte secretion of leptin, and circulating leptin levels may be increased in papillary thyroid cancer patients." (PMID 32645835, 2020). "Migration in vitro of papillary thyroid carcinoma cells is increased by leptin." (PMID 32645835, 2020). "Leptin has also been shown to enhance the migration of papillary thyroid cancer." (PMID 29577664, 2018). "Moreover, leptin and OBR expression levels in papillary thyroid cancer samples are associated with tumor size." (PMID 30627158, 2018). "Increased expression of leptin and its receptor in papillary thyroid cancer has been proved." (PMID 22007338, 2011). "Similarly, in papillary thyroid cancer, leptin increased its ability to migrate." (PMID 34202922, 2021). "Finally, we have also pointed out in the current review that leptin may be a trophic factor for papillary thyroid carcinoma, a form of cancer known to express the leptin receptor." (PMID 32645835, 2020). "However, a significant increase of serum leptin levels in Iranian patients with papillary thyroid carcinoma maybe used as a reliable marker to diagnose or confirm papillary thyroid cancer." (PMID 22007338, 2011). "In anoher papillary thyroid cancer (BHP2-7) cell line, there was an inhibitory effect of OB3 on the expression of GLUT2 and GLUT5, but leptin induced GLUT1 transcription." (PMID 27050378, 2016). "In papillary thyroid cancer cell lines, OB3 and leptin reduced the expression of PCNA and MCL1 in BHP18-21, however, only leptin reduced the expression of PCNA and c-Myc in BHP2-7 cells." (PMID 27050378, 2016).
papillary thyroid cancer (continued). "In papillary thyroid carcinoma, higher leptin levels were connected with a more advanced clinical stage, but without differences in serum leptin concentrations with respect to tumor size." (PMID 37444627, 2023). "Leptin and Ob-R have negative prognostic significance in papillary thyroid cancer, while Ob-R may play a protective role in anaplastic thyroid cancer." (PMID 27050378, 2016). "Although leptin and Ob-R expression are strongly correlated with older age, larger tumor size, nodal metastasis and advanced stage in clinical studies of papillary thyroid cancer, our results and those of others show that leptin does not stimulate cell proliferation." (PMID 27050378, 2016). "Compounding the complexity of leptin's role in carcinogenesis is that leptin may have differential responses in closely related cells; leptin induces migration in papillary thyroid cancer cells but not in anaplastic and follicular thyroid cancer cells." (PMID 22263109, 2012). "On the other hand, neither OB3 nor leptin activated the ERK1/2 or PI3K signal transduction pathways in follicular and papillary thyroid cancer cells (results not shown)." (PMID 27050378, 2016). "We found that leptin, but not OB3, stimulated the invasiveness of anaplastic thyroid cancer cells and reduced adhesion of papillary thyroid cancer cells." (PMID 27050378, 2016). "Leptin and its derivative, OB3, both significantly reduce abundance of MMP9 mRNA in follicular thyroid cancer cells, but do not affect expression of MMP9 in papillary thyroid carcinoma cells." (PMID 32645835, 2020).
renal fibrosis (16 papers, 2010 to 2025). A final common manifestation of a wide variety of chronic kidney diseases characterized by glomerulosclerosis and tubulointerstitial fibrosis. "Ang II, through its signalling receptor, AT1, may also stimulate the SMAD-dependent pathway during the EMT, causing renal fibrosis; and leptin also induces TGF-ß1 expression." (PMID 31120873, 2019). "Visceral adipose tissue secretes pro-inflammatory cytokines and adipokines, such as leptin and resistin, which not only induce oxidative stress but also promote renal fibrosis and dysfunction." (PMID 39940350, 2025). "In murine models of uremic cachexia and renal fibrosis, the use of leptin antagonists significantly reduced levels of TGF-β1 mRNA, which can be coactivated by leptin to promote the development of muscle and renal fibrosis." (PMID 37927592, 2023). "Folate-deficient diets further elevated serum TC, LDL-cholesterol, IL-6, tumor necrosis factor (TNF)-α, MCP-1, TGF-β1, and leptin, but decreased IL-10 level, and thus exacerbated renal fibrosis." (PMID 37630806, 2023). "Many adipokines, including leptin, adiponectin, vascular endothelial growth factor, angiopoietins, and resistin, play a role in extracellular matrix accumulation, leading to renal fibrosis." (PMID 34940593, 2021). "Leptin induces proliferation, differentiation and function of haemopoietic cells including T cells and plays a role in renal fibrosis." (PMID 29296203, 2017). "Several synthesized adipokines, including but not limited to leptin, adiponectin, vascular endothelial growth factor, angiopoietins, and resistin, play crucial roles in extracellular matrix accumulation, ultimately culminating in renal fibrosis." (PMID 38139229, 2023). "Many adipokines, including leptin, adiponectin, vascular endothelial growth factor, angiopoietins, and resistin, play crucial roles in the accumulation of extracellular matrix, ultimately leading to renal fibrosis." (PMID 38139229, 2023). "In addition, patients with renal fibrosis have higher level of plasma leptin, which was due to the increased leptin production." (PMID 21304902, 2011). "Indeed, activation of the p38/MAPK signaling pathway is involved in leptin-mediated renal fibrosis." (PMID 36726470, 2022). "The alterations in the levels of adipokines, especially high leptin and low adiponectin levels, contribute to oxidative stress, increase sympathetic nervous system activity, cellular hypertrophy, extracellular matrix accumulation, proteinuria, and renal fibrosis." (PMID 36461016, 2022). "Thus far, leptin has been considered to play an important role in progressive renal fibrosis." (PMID 21304902, 2011). "It has been hypothesized that the synthesis of leptin in HF pertains to cardiac and renal fibrosis and WAT and microvascular inflammation and that leptin-mediated neurohormonal and proinflammatory activation may enhance the expression of SGLT2 in the kidney tubules." (PMID 33240938, 2020).
anemia (15 papers, 2012 to 2024). A reduction in the number of red blood cells, the amount of hemoglobin, and/or the volume of packed red blood cells. "This study investigated and compared the relationships between hepcidin and leptin levels, iron status, and body fat to understand better the risk of iron deficiency anemia in endurance runners and sprinters." (PMID 34136516, 2021). "We demonstrated a strong and independent association between lower circulating leptin levels and low BMI, anemia, and reduced albumin levels in CKD patients." (PMID 27307101, 2016). "The purpose of the present study was to evaluate serum leptin levels and its associations with anemia, nutrition and bone metabolism biochemical parameters in stage 5 CKD patients, and investigate the longitudinal changes in these relationships after PTX." (PMID 27307101, 2016). "To examine the association of serum leptin level with anemia in hemodialysis, we investigated 36 patients (males: 21, diabetics: 11) under regular hemodialysis." (PMID 28197430, 2012). "Studies regarding the association of serum leptin with anemia in regular hemodialysis patients are quiet scarce." (PMID 28197430, 2012). "We found that blood cells of patients with ICUS, CCUS and MDS all have a significantly hypermethylated LEP promoter compared to healthy controls and that LEP hypermethylation is associated with anemia, increased bone marrow blast percentage, and lower plasma leptin levels." (PMID 37237325, 2023). "Therefore, this study investigated the relationships between hepcidin and leptin, iron status, and body fat to understand better the risk of iron deficiency anemia in endurance runners and sprinters." (PMID 34136516, 2021). "Patients with anemia had higher LEP promoter methylation compared to patients with normal hemoglobin levels (p = 0.009)." (PMID 37237325, 2023). "Higher levels of inflammatory markers, IL-6, leptin, hepcidin, ferritin, and ROS all contribute to anemia in cancer subjects." (PMID 36558514, 2022). "Among categorical variables, there was a difference in plasma leptin levels for menopausal status at T1 and T3 (P = 0.002 and 0.01 respectively), for anaemia status at T2 (P = 0.02) and the type of chemotherapy at T2 (P = 0.03)." (PMID 31016867, 2019). "Consistently, leptin values were found to be a predictor of EPO responsiveness in people with kidney failure with anemia." (PMID 30294279, 2018). "Interestingly, we show that patients with anemia had a significantly hypermethylated LEP promoter compared to patients with a normal hemoglobin level." (PMID 37237325, 2023). "Serum leptin was related to anemia, albumin, and bone metabolism disorders in CKD patients." (PMID 27307101, 2016). "Chronic selenosis in P. przewalskii resulted in symptoms such as weight loss, anemia, and lack of vitality, which may be related to abnormal phenylalanine metabolism, resulting in abnormal leptin levels." (PMID 37755262, 2023). "Higher levels of inflammatory markers, interleukin-6, and leptin; hepcidin levels; ferritin levels; EPO levels; and reactive oxygen species (ROS) all contribute to the incidence of anemia in cancer patients." (PMID 35464620, 2022). "There were statistical interactions between leptin and first-trimester BMI category on GWG percent adequacy (p-interaction = 0.02), between leptin and baseline maternal anaemia on inadequate GWG (p-interaction = 0.04), and between leptin and maternal stature on excessive GWG (p-interaction = 0.02)." (PMID 34615489, 2021). "However, because anemia in cancer patients is related to the nutritional state that affects the levels of iron, vitamins and other micronutrients useful for erythropoiesis, it is not surprising that a sensitive nutritional marker such as leptin is correlated with Hb levels." (PMID 30294279, 2018).
autism (15 papers, 2012 to 2024). Persistent deficits in social interaction and communication and interaction as well as a markedly restricted repertoire of activity and interest as well as repetitive patterns of behavior. "Recent studies have associated elevated plasma leptin levels in early childhood with a higher incidence of autism, as observed in the Boston Birth Cohort." (PMID 38951775, 2024). "Inclusion of weight in the model, that adjusted for the confounding effect, lead to disappearance of the significant association between Leptin and autism which was detected previously in the bivariate analysis." (PMID 34493761, 2021). "Elevated early childhood leptin levels in plasma, but not in cord blood, have been associated with an increased risk for autism, and associations between leptin levels and other behaviors have been reported from rodent models." (PMID 32494038, 2020). "In addition to adiponectin, autism has also been associated with changes in other adipokines, such as leptin." (PMID 38297246, 2024). "A study comparing 70 children diagnosed with ASD to 99 age-matched control children reported a significant increase in leptin levels in autism, with higher levels observed in early onset cases compared to regressive autism." (PMID 38951775, 2024). "Recent works found elevated plasma leptin levels in children with autism compared to typically developing controls." (PMID 38066466, 2023). "Biomarkers linked to autism and/or pioglitazone were also studied to attempt to understand the mechanisms involved, namely, IL-6, TNF-alpha, MCP-1, insulin, and leptin." (PMID 29791472, 2018). "Neuroimmune biomarkers linked to autism and/or pioglitazone, namely, IL-6, tumor necrosis factor (TNF)-alpha, monocyte chemotactic protein (MCP)-1/CCL2, insulin, and leptin, were also studied." (PMID 29791472, 2018). "Leptin, which is a potential biomarker of autism, is an example of a hormone involved in this process, and elevated leptin levels predict placental dysfunction." (PMID 29343227, 2018). "Elevated plasma leptin levels were reported in children with regressive autism (n = 37), compared with typically-developing controls (n = 50)." (PMID 22747567, 2012). "Another paper reported significantly higher leptin values in 35 patients with autistic disorder aged 180 14.1 ± 5.4 years old versus controls both at baseline and after one year of follow-up." (PMID 22747567, 2012). "Notably, studies have observed a higher concentration of leptin in the anterior cingulate gyrus of individuals with autism compared to controls." (PMID 38951775, 2024). "According to the previous evidence, abnormal secretion of some hormones, such as adiponectin, leptin, ghrelin, insulin, and IGF-1 may cause changes in the growth process, especially in early life, and may be associated with the risk of autism." (PMID 38066466, 2023). "Leptin, adiponectin and resistin are the only three molecules that belong exclusively to the class of adipokines and they have been studied in a limited number of researches concerning autism." (PMID 31835709, 2019). "The leptin analyses were performed because of their relation with both autism and pioglitazone." (PMID 29791472, 2018). "Similarly, another case-control study reported significantly increased leptin levels (p ≤ 0.01) in a small group of 31 lean pre-pubertal children with autism (ages ranged from 3 to 8 years with mean ± SD = 5.59 ± 2.26 years) compared to 28 healthy age- and sex-matched controls." (PMID 36902307, 2023).
experimental autoimmune encephalomyelitis (15 papers, 2011 to 2025). An autoimmune demyelinating disease of the central nervous system that is produced experimentally in animals by the injection of homogenized brain or spinal cord in Freund's adjuvant. "Previous reports showed that adoptive transfer of autoreactive T cells in leptin deficient mice reduced pathogenicity and decreased frequencies of Th1 and Th17 cells in the experimental autoimmune encephalomyelitis model." (PMID 31736971, 2019). "Leptin deficient mice (ob/ob) are resistant to the induction of experimental autoimmune encephalomyelitis (EAE), the animal model of MS." (PMID 24215402, 2013). "IF induced similar alterations in human leptin levels and gut microbiota to those in mice with experimental autoimmune encephalomyelitis." (PMID 37432222, 2023). "A previous report suggested that leptin reduces the number of immunosuppressive regulatory T cells in an experimental autoimmune encephalomyelitis (EAE), an animal model of multiple sclerosis." (PMID 28091609, 2017). "Leptin blockade in experimental autoimmune encephalomyelitis (EAE) improves clinical score, disease progression and relapses by inhibition of T cell proliferation and cytokine secretion toward a Th2/regulatory profile." (PMID 26589684, 2015). "Reduced leptin levels may ameliorate experimental autoimmune encephalomyelitis, an animal model of MS, by delaying disease onset and improving clinical symptoms." (PMID 34894407, 2022). "Consequently, leptin-deficient (obese mouse) mice were resistant to the onset of experimental autoimmune encephalomyelitis (EAE), which the administration of exogenous leptin reversed." (PMID 36237764, 2022). "Similarly, administration of leptin to mice without leptin deficiency but susceptible to experimental autoimmune encephalomyelitis (EAE) worsens the disease course, while the administration of anti-leptin receptor antibodies ameliorates it." (PMID 40019662, 2025). "It has been shown that leptin-deficient mice were resistant to experimental autoimmune encephalomyelitis, an animal model of human MS and that this adipokine can affect the survival and proliferation of autoreactive CD4(+) T cells in experimental autoimmune encephalomyelitis." (PMID 21935388, 2011). "Leptin plays a key role in the induction and maintenance of an effective proinflammatory immune response in the CNS by modulating pathogenic CD4+ cells, and mice lacking circulating leptin do not develop experimental autoimmune encephalomyelitis (EAE) after immunization." (PMID 33918133, 2021).